MMP9 (matrix metallopeptidase 9)
Diseases named in the same sentence as MMP9 in open-access papers (continued):
Sharing a sentence is not in itself a finding about the gene and the disease.
breast carcinoma (continued). "SNCG levels positively correlated with those of MMP-9 in breast cancer tissues and SNCG overexpression in retinoblastoma cells upregulated the expression of MMP9 through activation of AP-1 cis element." (PMID 29903032, 2018). "Strikingly, in MDA-MB-231 breast cancer cells, the loss of mdig appeared to favor the open chromatin structure of the genome for metastatic genes CXCL12, CXCR4, MMP-1, and MMP-9, while enhancing the formation of closed chromatin for UPA." (PMID 30254753, 2018). "The anticancer activity of silibinin is associated with the suppression Wnt/LRP6 signaling and also downregulates the TPA-induced MMP-9 expression through inhibiting COX-2 expression in breast cancer cells." (PMID 29681985, 2018). "To this end, we developed HDN-TIMP2,V3: a novel bi-specific heterodimer that successfully inhibits both MMP-9 activation and IL-17A-induced cytokine secretion to synergistically inhibit the invasion of breast cancer cells." (PMID 29983876, 2018). "Recently, a meta-analysis comprising 28 studies indicated that MMP-9 expression in serum and tumor tissue acts as a predictor for worse prognosis in breast cancer." (PMID 30241470, 2018). "Increased MMP-9 expression is observed in a wide range of tumor types, including gastric, CRC, and breast cancer in diverse cell types, and is associated with poor outcomes." (PMID 30500835, 2018). "Several distinct CD44 isoforms co-precipitated with MMP-9 in mouse mammary carcinoma and human melanoma cells and this interaction is believed to help localize MMP-9 to the cell surface." (PMID 29747682, 2018). "As accumulating evidence suggests the prognostic role of MMP-9 in breast cancer, the TNBC cells highly expressed MMP-9, whereas MMP-2 up-regulation was not consistent in various TNBC cell lines." (PMID 30185799, 2018). "Overexpression of MMP-2 and MMP-9 is observed in various types of cancer, such as colorectal tumors, melanoma and breast cancer." (PMID 29713337, 2018). "We note that the controversy remains over the influence of 1562 C/T (rs 3918242) of the MMP-9 on the genesis of breast cancer." (PMID 30352460, 2018). "In the present study, the activity of MMP-9 was found to be decreased by casticin in breast cancer cells, as confirmed by gelatin zymography." (PMID 30401729, 2018). "The purpose of this study was to examine the activity levels of MMP-2 and MMP-9 in a cohort of 80 surgical samples of breast cancer patients, and to uncover their putative correlations with the proteomic assembly of the same patients." (PMID 30060564, 2018). "Previous reports suggest that OPN regulates tumor progression and angiogenesis through regulation of VEGF, Cox2 and MMP-9 expression and activation in melanoma and breast cancer cells." (PMID 29310608, 2018). "Hispolon hinders the invasion of MDA-MB-231 breast cancer cells by inhibiting the MMP-9 expression through the NF-κB pathway." (PMID 29642589, 2018). "MMP-2 and MMP-9 activation can particularly enhance tumor cell metastatic potential in breast cancer." (PMID 29423083, 2018). "In another recent study, researchers found that, in breast cancer tissues, MMP-9 and MMP-2 expression levels were correlated with lymph node metastasis and tumor staging." (PMID 30262739, 2018). "This study evaluated MMP-9 expression in relation to various clinicopathological parameters in breast cancer." (PMID 30142200, 2018). "In breast cancer, however, MMP-9 has been traditionally studied as a tumor cell–derived peptidase and, to a lesser extent, as an immune cell protein, participating in regulation of tumor microenvironment and immune cell infiltrate." (PMID 30558648, 2018). "For example, studies have shown that MMPs are expressed in feline tumors, including MMP9 and MMP2, in feline meningioma and mammary cancer, and MMP9 in feline lymphoma." (PMID 30104530, 2018). "Resveratrol used in in vivo testing reduced expression of COX-2 and MMP-9, accompanied by reduced NF-κB activation in rat breast cancer tumors." (PMID 30092754, 2018).
breast carcinoma (continued). "Tissue plasminogen activator (tPA) and urokinase plasminogen activator (uPA) are known to activate pro-enzyme forms of MMP-2 and MMP-9 to active forms and tPA and uPA have been proposed as markers for breast cancer progression." (PMID 28880889, 2017). "Assessment of MMP9 by in-gel gelatin-zymography assays showed that TNF and TGF-β cytokines induced secretion of MMP9 by breast cancer cells and this was further enhanced by co-treatment with both cytokines together." (PMID 28977919, 2017). "The dimerization of HER3 and HER2 synergistically increases heregulin-β1-induced MMP-1 and MMP-9 expression in breast cancer cells." (PMID 28881584, 2017). "Recently, TBC1D3 was showed to enhance GF signaling, which has also been shown to stimulate the expression of MMP-9 at the transcriptional level in breast cancer cells." (PMID 28422741, 2017). "The present study mainly focused on the analysis of synergistic effects of three functional SNPs of MMP1 (rs1799750) -1607 1G/2G, MMP3 (rs35068180) -1171 5A/6A and MMP9 (rs3918242) -1562 C/T genes in relation to breast cancer development and progression." (PMID 28961241, 2017). "In breast cancer cells, expression of MMP9 was stimulated by individual cytokines and this was further enhanced when cells were treated with both cytokines concurrently." (PMID 28423685, 2017). "These authors also showed that several isoforms of CD44, expressed on murine mammary carcinoma cells, provide cell surface docking receptors for proteolytically active MMP9." (PMID 28191466, 2017). "Flavonoids such as quercetin and EGCG have been shown to decrease the expression of both MMP2 and MMP9 in human melanoma cells and breast cancer, respectively." (PMID 28947953, 2017). "Taken together, these data indicate that CaM enhances the TBC1D3-induced migration of human breast cancer cells by a mechanism involving the expression and activation of MMP-9." (PMID 28422741, 2017). "Work from Kim and colleagues highlighted the role of this cytokine in upregulation of MMP-2 and MMP-9 in the MCF10A breast cancer cell line; it is also known that these MMPs participate in TGFβ cleavage for further cytokine release." (PMID 28633655, 2017). "Together, these data indicate that TBC1D3 promotes the migration of human breast cancer cells in a manner involving the expression and activation of MMP-9." (PMID 28422741, 2017). "Studies suggested that genes, such as MMP2, MMP9, MMP11 and uPA, were found to be associated with breast cancer progression, angiogenesis and metastasis." (PMID 28388580, 2017). "To ensure these findings, we employed another invasive breast cancer cell line, Hs 578T cells were transfected with control siRNA or MMP9 siRNA, and then followed by treatment of combinations of HI-TOPK-032 or LPS." (PMID 28212583, 2017). "For example, MMP9 has high levels of expression in breast cancer, especially in breast cancer with strong capacity for distant metastasis." (PMID 28490334, 2017). "Evidence also exists showing overexpression of MT increases expression of MMP-9 in a human breast cancer cell line and increased presence of Zn(II) on MT increases MMP-9's ability to breakdown collagen." (PMID 29321743, 2017). "Snail expression in MCF-7 breast cancer cells increased MMP-9 expression and promoted the breakdown of basement membrane." (PMID 28152502, 2017). "In fact, knockdown of MMP9 in metastatic breast carcinoma cells significantly reduces tumor vasculature." (PMID 28423685, 2017). "Pretreatment with extract significantly decreased the levels of IL-8, IL-6, MMP-2 and MMP-9 in the breast cancer cells." (PMID 28264501, 2017). "MMP-9, is the main extracellular matrix protein-degrading enzyme known to play an important role in breast cancer cell migration and invasion." (PMID 29179450, 2017). "Our findings are in line with previous report demonstrating that ALT inhibits migration and suppresses expressions of COX-2 and MMP-9 in breast cancer cells." (PMID 28740138, 2017).
breast carcinoma (continued). "MMP9 has been shown to be involved in the migration and invasion of various tumors, including breast cancer, transitional cell carcinoma, and non-small cell lung cancer." (PMID 28410203, 2017). "Our study confirms the reported stimulating effects of AngII on breast cancer cell migration, invasion and activation of pro-metastatic factors such as MMP-9 and VEGF, supporting the notion that AngII can promote tumor cell growth and metastasis progression." (PMID 29179450, 2017). "GF signaling has been shown to stimulate the expression of matrix metalloproteinases-9 (MMP-9), one of human zinc-binding endopeptidases, in breast cancer cells." (PMID 28422741, 2017). "OL (370 μmol/L) reduced breast cancer cell growth and the expression levels of MMP-9 and MMP-2, and induced apoptotic cell death of breast cancer cells." (PMID 28410190, 2017). "Metastatic breast carcinoma MDA-MB-231 cells exhibit autocrine TGF-β signaling that contributes to MMP9-driven tumor angiogenesis." (PMID 28423685, 2017). "IL-8 as well as VEGF are involved in tumor angiogenesis and metastasis in breast cancer, while MMP-9 is related to the degradation of the extracellular matrix and tumor cell invasion." (PMID 28763032, 2017). "The current study found that fibroblasts enhance breast carcinoma growth by promoting the tumor vasculature via the MMP9-dependent mechanism." (PMID 28423685, 2017). "Our findings revealed that fibroblasts enhance breast carcinoma growth by promoting the tumor vasculature via the MMP9-dependent mechanism." (PMID 28423685, 2017). "In summary, the current study provides evidence that tumor-associated fibroblasts promote tumor angiogenesis by stimulating expression of the angiogenic driver MMP9 in breast carcinoma cells." (PMID 28423685, 2017). "It has also been shown that WNT5A impairs breast cancer cells invasion partly by reducing MMP9 activity." (PMID 28886116, 2017). "Our study reveals that fibroblasts can promote tumor vascularization by acting directly upon breast carcinoma cells to stimulate expression of pro-angiogenic MMP9." (PMID 28423685, 2017). "The rationale behind this is that WNT5A signaling is known to impair invasion of breast cancer cells in part by reducing extracellular MMP9 activity." (PMID 28886116, 2017). "Only in a very severe case of NM, a 53-year old patient with progressive breast cancer with severe neurologic deficits and diagnosis based on CSF cytology, we were able to detect MMP-9 and TNF-RI (as ADAM17 substrate) by ELISA." (PMID 28806983, 2017). "The levels of mRNA expression of NF-κB target genes uPA, PAI-1, CXCR4 and MMP-9, all of which strongly correlate with breast cancer metastasis, were measured using quantitative real time PCR." (PMID 28402272, 2017). "In breast cancer, Msln was reported to increase the production of matrix metallopeptidase 9 (MMP-9) which is an important factor in blood vessels formation and invasion." (PMID 27626699, 2016). "In a breast cancer model, IgG purified from the blood of breast cancer patients stimulated muscarinic acetylcholine receptors to regulate cell migration and metalloproteinase-9 (MMP-9) activity in the breast cancer cell line MCF7." (PMID 28536629, 2016). "Simultaneous silencing of uPA and MMP9 in breast cancer cells decreased the wound healing, migratory, invasive and adhesive capacity of the cells." (PMID 26906973, 2016). "Some previous studies reported independently that breast cancer patients with high serum or tumor MMP-9 expression showed a poor prognosis." (PMID 27110764, 2016). "TAMs are thus responsible for the production of VEGF, of urokinase-type plasminogen activator (uPA), and of matrix metalloproteinase-9 (MMP-9) in human breast carcinomas." (PMID 28053982, 2016). "Kaempferol can inhibit cancer cell invasion by interrupting the PKCδ/MAPK/AP-1 cascade and subsequently down-regulating MMP-9 expression in MDA-MB-231 human breast carcinoma cells." (PMID 27999314, 2016).
breast carcinoma (continued). "Neutralization of BMP-4 in NDRG2-expressing breast cancer cells results in the rescue of MMP9 mRNA expression and migration capacity." (PMID 26506239, 2016). "Among others, MMP-9 is the main MMP to digest basement membrane collagen and MMP-2 is found to be positively associated with breast cancer progression." (PMID 27110769, 2016). "MMP2 and MMP9 are secretory proteins, but small amounts of the enzymes have consistently been found on the surface of various cells, including breast cancer cells." (PMID 27042827, 2016). "After successful knockdown of the uPA and MMP9, we have investigated the sustaining invasive capacity of the breast cancer cells." (PMID 26906973, 2016). "Previous reports indicated that fibronectin, possibly via α5β1 integrin, stimulates the production of MMP-9 in human laryngeal carcinoma cells, breast cancer cells, and T lymphocyte cell lines." (PMID 27602495, 2016). "At that time, online microarray data by Duvall-Noelle showed downregulation of MMP9 after LASP1 knockdown in breast cancer cells." (PMID 27588391, 2016). "Our recent work identified Rab40b GTPase as a protein required for MMP2 and MMP9 secretion from the invadopodia in breast cancer cells." (PMID 27789576, 2016). "In breast cancer, tumor cell-derived MMP9 drives malignant progression and metastasis of basal-like triple negative breast cancer." (PMID 27487154, 2016). "Increased expression of MMP9 has been detected in invasive/metastatic cancers such as colorectal cancer, gastric carcinoma, pancreatic carcinoma, breast cancer, and oral cancer." (PMID 27487154, 2016). "In the breast cancer patients, high MMP9 expression is related to tumor stage and lymph node metastasis." (PMID 26906973, 2016). "In breast cancer particularly, MMP9 has been found to be expressed in tumors expanding to secondary sites." (PMID 26922065, 2016). "Noteworthy, stratification of all hepatic cancer groups with respect to MMP-2 and MMP-9 activities revealed characteristic patterns specifically in patients with hepatic breast cancer metastases who had undergone SIRT." (PMID 27277077, 2016). "In our present work, two key molecules for metastasis, uPA and MMP9 have been knockdown in the breast cancer cells to check the cancer progression." (PMID 26906973, 2016). "We previously reported that WNT5A at least in part inhibits the migration and invasion of breast cancer cells by reducing the production and secretion of MMP9." (PMID 27623766, 2016). "The results also reported suppression of NF-κB expression via down-regulation of VEGF, COX-2, and MMP-9 expression in the breast cancer as well as in brain, lung, liver and spleen tissues." (PMID 27999314, 2016). "Previous studies have demonstrated that STAT3 signaling mediated up-regulation of MMP-9 expression and conferred increased invasion ability in multi-drug-resistant breast cancer cells." (PMID 27793010, 2016). "In keeping with this, CRP2-depleted breast cancer cells exhibited a reduced capacity to promote ECM degradation, and to secrete and express MMP-9, a matrix metalloproteinase repeatedly associated with cancer progression and metastasis." (PMID 26883198, 2016). "In breast cancer patients, radiotherapy can increase the plasma level of MMP-9 and the level of MMP-2 was also significantly higher in skin biopsies of women after radiotherapy, relative to non-irradiated skin." (PMID 27282478, 2016). "As uPA and MMP9 has been known to degrade the ECM and aids the cells in migration, we first checked the expression level of the uPA and MMP9 in different breast cancer cell lines." (PMID 26906973, 2016). "Matrix metalloproteinase-9 (MMP-9), among other MMPs, is known to play an important role in breast cancer cell invasion and metastasis." (PMID 26888313, 2016). "TSA exhibits anti-invasive properties through upregulation of RECK, which further inhibits MMP-2 and MMP-9 in a variety of cell lines, including breast cancer cell lines and hepatocytes, amongst other cancer types." (PMID 27506904, 2016).